IGHV2-70D (immunoglobulin heavy variable 2-70D)
Description:
V region of the variable domain of immunoglobulin heavy chains that participates in the antigen recognition. Immunoglobulins, also known as antibodies, are membrane-bound or secreted glycoproteins produced by B lymphocytes. In the recognition phase of humoral immunity, the membrane-bound immunoglobulins serve as receptors which, upon binding of a specific antigen, trigger the clonal expansion and differentiation of B lymphocytes into immunoglobulins-secreting plasma cells. Secreted immunoglobulins mediate the effector phase of humoral immunity, which results in the elimination of bound antigens. The antigen binding site is formed by the variable domain of one heavy chain, together with that of its associated light chain. Thus, each immunoglobulin has two antigen binding sites with remarkable affinity for a particular antigen. The variable domains are assembled by a process called V-(D)-J rearrangement and can then be subjected to somatic hypermutations which, after exposure to antigen and selection, allow affinity maturation for a particular antigen.
Gene: Immunoglobulin variable (V) gene on chromosome 14 (106,723,574 to 106,724,093, reverse strand). Ensembl gene ENSG00000211974.
Subcellular location: Secreted; Cell membrane
Gene Ontology:
Molecular function: antigen binding
Biological process: immunoglobulin mediated immune response
Cellular component: extracellular region; plasma membrane
Homologues: Orthologues: mouse Ighv8-12 (72% identical), mouse Ighv8-6 (71% identical), mouse Ighv8-8 (71% identical), mouse Ighv8-9 (70% identical), mouse Ighv8-5 (69% identical), mouse Ighv8-11 (66% identical), rat AABR07065813.1 (66% identical), mouse Ighv8-4 (63% identical), mouse Ighv8-13 (62% identical), mouse Ighv8-2 (61% identical), rat Igh-6-ps1 (52% identical). Paralogues in human: IGHV2-70 (97% identical), IGHV2-5 (87% identical), IGHV2-26 (85% identical), IGHV2OR16-5 (85% identical), IGHV4-59 (54% identical), IGHV4-61 (54% identical), IGHV4-39 (53% identical), IGHV4-28 (52% identical), IGHV4-31 (52% identical), IGHV4-4 (51% identical), IGHV4OR15-8 (50% identical), IGHV4-34 (50% identical), and 65 more.